EEF2 (eukaryotic translation elongation factor 2)
Diseases named in the same sentence as EEF2 in open-access papers (continued):
Sharing a sentence is not in itself a finding about the gene and the disease.
tumor (continued). "TCGA analysis further confirmed that mRNA levels of EEF1A1, EEF1A2, EEF1B2, EEF1G and EEF2 were significantly downregulated in tumor tissues than normal." (PMID 29342219, 2018). "EEF1B2, EEF1G, EEF1D, EEF1E1 and EEF2, presented increased transcript levels in tumor group compared to normal, the most prominent being EEF1E1." (PMID 29342219, 2018). "Evaluation of eEF2 expression alone and combined with intensity detected a significant increase in tumor tissue (P<.001)." (PMID 28060762, 2017). "Hypoxic environments have been reported to induce eEF-2 activity, and we further showed that hypoxic conditions decreased the anti-tumour effect of lapatinib by the activation of eEF-2." (PMID 27756261, 2016). "DPH-1 is a tumor suppressor that is responsible for the first step of the unique protein modification that occurs on elongation factor 2 (eEF2), which converts a histidine residue to diphthamide." (PMID 23382692, 2013). "We identified different tumor- and hypoxia-specific antigens including the phosphorylated Thr56 form of the eukaryotic elongation factor 2 (eEF2)." (PMID 24130777, 2013). "Re-probing the 2D membrane used for SERPA confirmed that the spot recognized by the serum of tumor-bearing mice was also positively stained by a commercial anti-phospho-Thr56 eEF2 antibody." (PMID 24130777, 2013). "The treatment of tumor sections with phosphatase lambda completely abrogated the staining obtained with a commercial anti-phospho-eEF2 antibody." (PMID 24130777, 2013). "Treatment with both liposomal eEF-2K siRNA#1 and siRNA#2 resulted in significant down-regulation of its expression in the tumors, a decrease in phosphorylated eEF2 and significant inhibition of tumor growth." (PMID 22911754, 2012). "This targeting resulted in a substantial decrease in eEF2 phosphorylation in the tumors, and led to the inhibition of tumor growth, the induction of apoptosis and the sensitization of tumors to the chemotherapy agent doxorubicin." (PMID 22911754, 2012). "EEF2 is overexpressed in many tumor types and seems to play an important role in rendering tumor cells resistant to the translation-suppressing effects of hypoxia." (PMID 22548173, 2012). "Furthermore, in melanoma, β2-AR activation by (R, R')-MNF enhances eEF2 phosphorylation, leading to reduced expression of tumor regulators such as EGFR, cyclin A, and MMP-9, thereby suppressing tumor growth and progression." (PMID 39707196, 2024). "For instance, inhibitors that prevent eEF2 phosphorylation or methylation could lock eEF2 in its inactive form, thereby reducing its role in tumor proliferation." (PMID 39707196, 2024). "Additionally, the fusion toxin tagraxofusp, which targets CD123 in tumor cells, exploits eEF2 ADP-ribosylation." (PMID 39707196, 2024). "Targeting of eEF2 with TSN inhibits ESCC tumor growth in vitro and in vivo." (PMID 37088855, 2023). "However, significant overexpression of EEF1A2, EEF1G, EEF1D, EEF1E1 and EEF2 was seen in tumor tissues." (PMID 29342219, 2018). "Also, the injection of HCT116 cells into mice led to the development of a tumor with a robust staining of phospho-Thr56 eEF2 confirming the occurrence of this post-translational modification in vivo." (PMID 24130777, 2013). "Using a specific immunoassay, we could detect the presence of corresponding anti-phospho-Thr56 eEF2 aAb in the serum of tumor-bearing mice (vs healthy mice)." (PMID 24130777, 2013). "The activity of eEF2 is increased in several tumor types including breast cancer." (PMID 23102376, 2012). "Therefore, targeting eEF2 is an effective strategy for slowing tumor growth." (PMID 40698138, 2025). "Therefore, eEF2 is a potential target for tumor immunotherapy in multiple cancers." (PMID 35127825, 2021).
tumor (continued). "Further important findings include the tumour specific expression of alanyl-, glycyl- and seryl-tRNA synthetases which catalyze the transfer of specific amino acids to tRNA, as well as regulation of eukaryotic translation elongation factor 2 and Poly(rC) protein 2 that binds to oligo dC." (PMID 25872475, 2015). "The results demonstrated that EEF2, G3BP1, G3BP2, PRPF8, RECQL4, STOML2, and UBB exhibited significantly higher expression levels in the majority of tumor tissues, whereas METTL3 and NR2C2 showed a widespread downregulation trend." (PMID 41341921, 2025). "eEF2 and phosphorylated eEF2 are prognostic indicators of HCC patient survival, and that eEF2 kinase promotes HCC angiogenesis and tumor progression through SP1/KLF5-mediated VEGF expression." (PMID 37740172, 2023). "CLDN7, PRKCB, EEF2 and TFRC protein levels were all found at higher levels in high LN yield tumours (q = 0.0283)." (PMID 35043009, 2022). "Quantitative phosphoproteomics integrated with multiple bioinformatics analysis revealed a series of phosphopeptides and candidate proteins such as EEF2, U2AF2 and FLNC involved in tumor metastasis and invasion." (PMID 34437425, 2021). "The diphthamide on eukaryotic translation elongation factor 2 (eEF2) is the target of ADP-ribosylating toxins and -derivatives that serve as payloads in targeted tumor therapy." (PMID 28245596, 2017). "eEF2 is a member of the GTP-binding elongation factor family and catalyzes peptidyl-tRNA translocation from the ribosomal A site to the P site during protein synthesis; it is highly expressed in tumor cells with fast protein synthesis." (PMID 40698138, 2025). "While a kinase for Eef2 was reported to act as a tumor suppressor as well as a stimulator 50, 51, to the best of our knowledge, no reports were available for possible anti-tumor action of Eef2." (PMID 35547745, 2022). "Moreover, much of evidence proved that total eukaryotic elongation factor 2 (eEF2) and phosphorylated eEF2 at threonine 56 are prognostic markers for overall survival of HCC-patients and the regulating eEF2 kinase is a potential drug target for tumor therapy." (PMID 32760197, 2020). "The phospho-Thr56 eEF2 signal was already significantly increased at day 7 (p<0.05 vs. day 0) while at this time, the tumor was not yet detectable." (PMID 24130777, 2013). "AMPK or mTOR may phosphorylate eEF2 in the absence of active eEF2K, ensuring that protein synthesis is finely modulated to promote tumor survival under adverse conditions." (PMID 39592671, 2024). "After treated with the condensed virus, the average tumor volume and weight in the LEG107 and LEG244 cases were suppressed after silencing eEF2, while the average body weight of mice was not significantly changed." (PMID 37088855, 2023).
infection (26 papers, 2009 to 2025). The state of being infected such as from the introduction of a foreign agent such as serum, vaccine, antigenic substance or organism. "We also observed eEF2 phosphorylation during infection with the picornavirus CVB3, expressing protein 2C that contains NTPase activity, although 2C belongs to a different helicase superfamily." (PMID 36848386, 2023). "The increase in cAMP occurs much sooner in infection than the decrease in ATP, which matches the 2 h p.i. increase in eEF2 phosphorylation detected in the proteomics experiment." (PMID 36848386, 2023). "It is possible that the translational inhibition through eEF2 phosphorylation mostly affects newly transcribed mRNAs, which would be useful during infection to prevent expression of proteins involved in the innate immune response." (PMID 36848386, 2023). "For example, infection of human gastric adenocarcinoma (AGS) cells with wild-type or the cytotoxin-associated gene A (CagA) and virB7 mutants of H. pylori suppressed eEF2 phosphorylation at Thr-56 on eEF2K at 1 to 3 hours post-infection." (PMID 34532346, 2021). "Consistently, phosphorylation levels of eukaryotic elongation factor 2 (eEF2), reflecting altered binding to the ribosome and impaired elongation, remained unaltered during the course of infection." (PMID 28074025, 2017). "The regulation of eef-2 in the nematodes infected with K. pneumoniae was significantly downregulated during course of infection." (PMID 28932706, 2017). "By this time after infection, a similar localization was found for other translation initiation or elongation factors such as eIF3b, eIF2α and eEF2." (PMID 19714237, 2009). "We hypothesized that one of nsP2’s domains or activities may trigger a pathway that induces eEF2 phosphorylation during infection." (PMID 36848386, 2023). "Furthermore, we evaluated the effect of silencing eEF2 in vivo using a lentivirus intra-tumoral infection PDX murine model." (PMID 37088855, 2023). "In these other studies, samples were taken much later in infection (24 h p.i. or later) and eEF2 may have been degraded during this stage of infection." (PMID 36848386, 2023). "Furthermore, inhibitory Threonine-57 phosphorylation of the elongation factor EEF2 was clearly increased throughout the infection upon PP1 inhibition via 1E7-03." (PMID 34335531, 2021). "Our study provides evidence that this dephosphorylation might be mediated by PP1 and suggests a novel layer of AMPK regulation by inhibition of the AMPK/EEF2K/EEF2 axis via PP1 starting very early in infection." (PMID 34335531, 2021). "Inhibition of mTOR, followed by subsequent changes in host cellular activities and hyper-susceptibility of PI3 kinase, akt-1, mTOR, pdi-2, and eef-2 mutants unveiled the role of PI3K/AKT/mTOR pathway, protein folding, and translation machinery in host defense against infection." (PMID 28932706, 2017). "Hence, to investigate the status of translational regulatory gene in the C. elegans during infection, the mRNA level of eef-2 was examined." (PMID 28932706, 2017). "Little difference in total protein levels of AMPK, ACC or eEF2 was observed during infection." (PMID 22532801, 2012). "Finally, regulation of eEF2 expression was observed only in specific experimental conditions, such as for enrofloxacin in early infection compared to vehicle (^^, p<0.01) and for CaMKI with doxycycline in late infection compared to vehicle (^, p<0.05)." (PMID 39721265, 2024). "We next explored whether eEF2 phosphorylation also occurs upon infection with other viruses." (PMID 36848386, 2023). "In particular, these changes involved mTOR, BDNF, Akt, eEF2, CaMKI, and CREB-dependent signaling cascades in groups treated with monensin or enrofloxacin, and the fewest for doxycycline 15 days after infection." (PMID 39721265, 2024).
infection (continued). "eEF2 was also identified as an interaction partner of CHIKV nsP3 in a yeast two-hybrid assay and as an interaction partner of SINV nsP3 during infection with a nsP3-GFP expressing SINV mutant." (PMID 36848386, 2023). "Infection with CVB3 resulted in early eEF2 phosphorylation, but infections with EAV or HAdV did not." (PMID 36848386, 2023). "As expected, with the increase of multiplicity of infection (MOI) from 1000 to 10,000, the HDR events steadily increased but no significant changes of total editing efficiencies at both EEF2 and AAVS1 loci, accompanied by a considerable reduction of deletion indexes from ~ 2 to ~ 1%." (PMID 34416913, 2021). "Our study revealed that, during the earliest stages of infection, the alphavirus nsP2 NTPase triggers an increase in the intracellular cAMP concentration which results in activation of PKA and increased phosphorylation of eEF2 on T56 and inhibition of translation." (PMID 36848386, 2023). "Viral mRNAs are very abundant during infection and if translation is initiated more efficiently than on most cellular mRNAs this may increase their chance of being translated when there is less active non-phosphorylated eEF2 available for translation elongation." (PMID 36848386, 2023).
neurodegenerative disease (7 papers, 2018 to 2024). A disorder of the central nervous system characterized by gradual and progressive loss of neural tissue and neurologic function. "The importance of eEF2 in regulating ribosome activity has been highlighted by recent studies demonstrating that mutations in eEF2 in patients suffering from neurodevelopmental or neurodegenerative diseases impair translation fidelity." (PMID 38219816, 2024). "eEF2 is of great interest in neuron biology and pathology, with studies of its roles in neurodegenerative diseases helping to reveal previously unappreciated mechanisms of gene expression control." (PMID 32298235, 2020). "Future studies aiming to better understand neurodegenerative diseases and depression-like syndrome, combined with a circuit approach and behavioral paradigms will better link the eEF2 pathway and dopamine to establish the eEF2 pathway as a potential target for therapy." (PMID 32499677, 2020). "However, the importance of eEF2 phosphorylation in the normal brain has also been documented, illustrating the need for the cautious application of eEF2K inhibitors against neurodegenerative diseases." (PMID 32298235, 2020).
neurodevelopmental disorder (4 papers, 2022 to 2024). A behavioral and cognitive disorder with onset during the developmental period that involves impaired or aberrant development of intellectual, motor, or social functions. "A yeast model system previously examined the effects of two eEF2 mutations that mimic human eEF2 mutations associated with neurodevelopmental disorders, C372Y and P580H." (PMID 39652595, 2024). "An emerging body of research is revealing mutations in elongation factor eEF2 that are implicated in both inherited and de novo neurodevelopmental disorders." (PMID 36470424, 2022). "Variations and differentially expression of EEF2 cause neurodevelopmental disorders like Alzheimer." (PMID 36691005, 2023).
adenocarcinoma (2 papers, 2018 to 2022). A common cancer characterized by the presence of malignant glandular cells. "Likewise, elevated mRNA levels of EEF1B2, EEF1G and EEF2 were significantly correlated with worse survival outcome in adenocarcinoma." (PMID 29342219, 2018). "Hub genes were identified, including GADPH, ENO1, EEF2, and ATP5A1, which showed differential expression in patients with adenocarcinoma of the colon and rectum." (PMID 35445138, 2022).
cardiovascular disease (2 papers, 2017 to 2023). "The functions of eEF2 have been rarely studied in the context of cardiovascular diseases and deserve further investigation in DCM." (PMID 28427148, 2017). "In our study, one of these proteins, eEF2, was related to multiple cardiovascular diseases." (PMID 28427148, 2017).
inflammation (1 paper, 2023). Aberrant reaction of the microcirculation characterized by movement of fluid and leukocytes from the blood into extravascular tissues. "The downregulation of EEF2 protein mediated the lipopolysaccharide-induced acute pulmonary inflammation on microvascular endothelial cells." (PMID 37612724, 2023).
reproductive diseases (1 paper, 2023). "Understanding how lncRNA Gm2044/EEF2 protein regulates estradiol synthesis will help treat estrogen-related reproductive diseases." (PMID 37612724, 2023).
EEF2 also shares sentences with these, for which no sentence is quoted: Parkinson disease (3 papers); psychiatric disorder (3); acute myeloid leukemia (2); Ataxia (2); head and neck squamous cell carcinoma (2); leishmaniasis (2); pancreatic cancer (2); pertussis (2); age-related macular degeneration (1); alcohol (1); Arrhythmia (1); Autoimmunity (1); breast (1); catecholaminergic polymorphic ventricular tachycardia (1); cerebellar ataxia (1); Cerebral ischemia (1); cholera (1); coccidiosis (1); COVID-19 (1); Darier disease (1); Deep Venous Thrombosis (1); Down syndrome (1); episodic ataxia type 6 (1); esophageal adenocarcinoma (1); follicular lymphoma (1); gastric tumors (1); Gliosis (1); hematologic disorder (1); hereditary cerebellar ataxia (1); Infertility (1).
A further 23 diseases each share a sentence with EEF2 in 1 paper.